MKRN9P (makorin ring finger protein 9, pseudogene)
Synonyms: MKRN9; RNF65; formerly ZNF127L3; MKRN5; MKRNP6
Gene: Transcribed processed pseudogene on chromosome 12 (87,783,118 to 87,784,568, reverse strand). Ensembl gene ENSG00000258128.
Diseases named in the same sentence as MKRN9P in open-access papers:
MKRN9P is named in the same sentence as 1 disease in open-access papers, as found by Europe PMC text mining. Sharing a sentence is not in itself a finding about the gene and the disease. The quoted sentences say what the papers report.
cancer (1 paper, 2021). A tumor composed of atypical neoplastic, often pleomorphic cells that invade other tissues. "MKRN9P (Makorin pseudogene 9) is expressed mostly in the lung and cancers at low levels in FANTOM5 CAGE data." (PMID 34880903, 2021).